MYRFL (myelin regulatory factor like)
Synonyms: C12orf15; C12orf28; FLJ25056; bcm1377
Tractability: Antibody: UniProt predicts a signal peptide or a membrane-spanning region.
Gene: Protein-coding gene on chromosome 12 (69,825,227 to 69,959,097, forward strand). Ensembl gene ENSG00000166268.
Subcellular location: Membrane
Subcellular location (Human Protein Atlas): Nucleoli
Gene Ontology:
Molecular function: DNA-binding transcription factor activity; sequence-specific DNA binding; DNA binding
Biological process: positive regulation of DNA-templated transcription; protein autoprocessing; regulation of DNA-templated transcription
Cellular component: endoplasmic reticulum membrane; nucleus; membrane
Genetic constraint (gnomAD): Loss-of-function variants: 55 observed, 75.62 expected, observed/expected ratio (o/e) 0.73, 90% interval 0.58 to 0.91. The upper end of that interval is the gene's LOEUF score, 0.91, which puts it in group 3 of 6, group 1 being the genes least tolerant of losing a copy. Missense variants: 668 observed, 732.97 expected, observed/expected ratio (o/e) 0.91, 90% interval 0.85 to 0.97. Synonymous variants: 221 observed, 247.37 expected, observed/expected ratio (o/e) 0.89, 90% interval 0.8 to 1.
Homologues: Orthologues: chimpanzee MYRFL (99% identical), macaque MYRFL (96% identical), pig MYRFL (84% identical), mouse Myrfl (81% identical), guinea pig MYRFL (79% identical), rat Myrfl (79% identical), rabbit MYRFL (79% identical), dog MYRFL (77% identical), tropical clawed frog myrfl (55% identical), zebrafish myrfl (44% identical), Drosophila melanogaster CG3328 (33% identical), Caenorhabditis elegans myrf-2 (26% identical), and 1 more. Paralogues in human: MYRF (43% identical).
Diseases named in the same sentence as MYRFL in open-access papers:
MYRFL is named in the same sentence as 3 diseases in open-access papers, as found by Europe PMC text mining. Sharing a sentence is not in itself a finding about the gene and the disease. The quoted sentences say what the papers report.
Alzheimer disease (1 paper, 2023). A progressive, neurodegenerative disease characterized by loss of function and death of nerve cells in several areas of the brain leading to loss of cognitive function such as memory and language. "Further, four genes are correlated with neuropsychiatric traits such as behavioral disorders, panic disorders, or Alzheimer's disease (MYRFL, TNEN132, RNFT2, and PLA2G4A)." (PMID 37337823, 2023).
MYRFL also shares sentences with these, for which no sentence is quoted: behavioral disorders (1 paper); panic disorder (1).